MGP (matrix Gla protein)
Diseases named in the same sentence as MGP in open-access papers (continued):
Sharing a sentence is not in itself a finding about the gene and the disease.
steatosis (1 paper, 2025). Increased lipid within the cytoplasm of cells. "Notably, the antifibrotic effects of partial MGP deficiency occur without changes in hepatic lipid accumulation, supporting a role for MGP in fibrosis pathways rather than in the metabolic drivers of steatosis." (PMID 41303567, 2025).
systemic lupus erythematosus (1 paper, 2025). An autoimmune multi-organ disease typically associated with vasculopathy and autoantibody production. "T1MP1 and MGP were found to be co-enriched in pathways related to “aminoacyl trna biosynthesis”, “systemic lupus erythematosus”." (PMID 40299331, 2025).
urothelial carcinoma (1 paper, 2022). A malignant neoplasm derived from the transitional epithelium of the urinary tract (urinary bladder, ureter, urethra, or renal pelvis). "We also found that MGP was positive in only 2 of 218 cases (0.9%) of urothelial carcinoma, which is known to be frequently labeled with GATA3 (70–90%,)." (PMID 36284362, 2022).
valvular aortic stenosis (1 paper, 2022). "The circulating level of inactive MGP (dephosphorylated and uncarboxylated MGP, dp-ucMGP) is related to the severity of aortic calcification in patients with CKD, and predicts long-term mortality in patients with calcific valvular aortic stenosis." (PMID 39086959, 2022).
tumor (50 papers, 2008 to 2025). "High circulating levels of MGP in tumors have been linked to tumor aggressiveness and poor prognosis in breast cancer, glioblastoma, primary renal-cell carcinomas, prostate carcinomas, and testicular germ-cell tumors." (PMID 35053080, 2022). "Cellular differentiation in cancer and tumor progression has recently been linked to MGP expression." (PMID 35053080, 2022). "Furthermore, MGP expression correlates differently to metastatic spread depending on the tumor type and high expression associates with the metastatic spread in breast cancer." (PMID 41249124, 2025). "Additionally, MGP (Matrix Gla Protein), a calcium-binding protein, is integral to extracellular matrix remodeling and mineralization, and its elevated expression is associated with tumor aggressiveness and adverse prognosis." (PMID 41223185, 2025). "BL tumor cells exhibited elevated expression of MGP (matrix Gla protein), AZGP1 (alpha-2-glycoprotein 1), AGR2 (anterior gradient protein 2), TFF3 (trefoil factor 3), and FGFR1 compared to EP and LP cells." (PMID 39955556, 2025). "MGP has also been shown to become upregulated in later-stage cancers to increase tumor stabilization and perfusion." (PMID 40563443, 2025). "MGP has shown conflicting roles in cancer, including tumor suppression or promotion depending on the context." (PMID 41395115, 2025). "The biomarker signature identified in this study, more specifically AGER and MGP, has unique methylation patterns in tumor versus normal tissues." (PMID 40563443, 2025). "Through the robust machine learning approaches, we developed a four‐gene model (MGP, LOXL2, FSTL3, and PFN2) reflecting key biological processes associated with inflammatory CAF activity and tumor aggressiveness." (PMID 41395115, 2025). "For example, the tumour cell expressed genes CD24, CLU, and SLPI35–37 and the infiltrating cell expressed genes GPNMB, MGP, GPX3, and MFAP438–41 have all been previously associated with poor prognosis and chemotherapy resistance in HGSOC." (PMID 38570491, 2024). "It is intriguing that MGP, in turn, promotes the peritoneal adhesion and invasion of tumor cells, which points to this protein as a master regulator of the bi-directional crosstalk between the TME and OCSC." (PMID 36977707, 2023). "MGP has also been found aberrantly expressed in different cancer types, including OC, where its level of expression often correlates with tumor aggressiveness." (PMID 36977707, 2023). "In agreement with the results on genetically manipulated OVCAR3 cells, MGP increased dramatically the tumor-initiating potential of COV318 cells." (PMID 36977707, 2023). "The mRNA expression levels of three key genes (USP34, C3 and MGP) based on TCGA tumor data were also determined, and the USP34 gene was highly expressed in the cancer cell lines included in the T-LBL and T-ALL datasets according to CCLE analysis." (PMID 37664545, 2023). "NOD/SCID/IL2Rgamma-null mice were inoculated subcutaneously with OVCAR3 or COV318 genetically manipulated for MGP expression and monitored for tumor development." (PMID 36977707, 2023). "For instance, MGP, an ECM protein, has been implicated in carcinogenesis and its dysregulated expression observed in multiple tumor types." (PMID 37777759, 2023). "MGP was found to be consistently upregulated in post-treatment samples, suggesting that chemotherapy promotes an enrichment in MGP-expressing tumor cells." (PMID 36977707, 2023). "We then calculated scores for SLS and IS within identified tumor spots using the most robust marker genes MGP (for SLS) and ACTA2 (for IS), and identified islands enriched with SLS (blue) or IS (green)." (PMID 36028490, 2022). "MGP was recently found to be overexpressed in various types of cancer and was reported to promote tumor progression by regulating angiogenesis." (PMID 36284362, 2022).
tumor (continued). "The MGP action of favoring metastasis spread can be explained by its effects of altering endothelial adhesion and the tumor cell’s extravasation ability and by modulating metalloproteinase activities." (PMID 35053080, 2022). "Wang and his team established a model for predicting the postoperative survival of ESCC by using UBE2C and MGP genes, as well as the clinicopathological factors including the tumor staging and grade." (PMID 33859939, 2021). "Previous studies showed aberrant expression of MGP in various types of cancers and exert dual biological functions, acting as an oncogene or tumor‐suppressor, by regulating the expression of different target genes (Gheorghe and Crăciun, 2016)." (PMID 32086862, 2020). "In our study, the patients with higher MGP expression levels exhibited a worse prognosis than others, which is consistent with the tumor progression‐promoting role of MGP suggested in our in vitro studies by using GC cell lines." (PMID 32086862, 2020). "It has been additionally suggested that MGP expression is related to cellular differentiation and tumor progression." (PMID 30257426, 2018). "To evaluate the potential use of UBE2C and MGP as biomarkers for ESCC, we analyzed the protein levels of UBE2C and MGP in 205 training ESCC tumor tissues by immunohistochemistry (IHC)." (PMID 27556859, 2016). "The positive rates of UBE2C and MGP in ESCC tumor tissues were up to 43.4% (89/205) and 41.5% (85/205), respectively." (PMID 27556859, 2016). "The positive rates of UBE2C and MGP in ESCC tumor tissues were up to 56.5% (117/207) and 53.6% (111/207), respectively." (PMID 27556859, 2016). "The Cox regression analysis showed that T stage, lymph nodes status, TNM stage, tumor grade, vascular invasion, UBE2C expression and MGP expression were significantly associated with overall survival (OS) (p<0.05)." (PMID 27556859, 2016). "For training cases, univariate analysis showed that the factors of T stage, lymph nodes status, TNM stage, tumor grade, UBE2C expression and MGP expression were significantly associated with disease-free survival (DFS) (P<0.05)." (PMID 27556859, 2016). "The survival prediction model consisting of two genes (UBE2C and MGP) and two clinicopathological factors (tumor stage and grade) was developed." (PMID 27556859, 2016). "Moreover, CM of cancer tissue explants resulted in different gene expression profiles than the CM of adjacent normal breast tissue, including a trend to upregulate MGP, suggesting that soluble factors in the tumor microenvironment influence LEC phenotype." (PMID 41249124, 2025). "Importantly, through integrative machine learning approaches, we identified four hub genes (MGP, LOXL2, FSTL3, and PFN2) that are closely associated with tumor development and progression." (PMID 41395115, 2025). "Hence, MGP exerts diverse roles with regard to the tumor environment and tumor type, and more in-depth research is required to pinpoint its specific role and importance." (PMID 41249124, 2025). "In contrast, domain 13, with high expression of MGP, CPB1, and S100G, points to a region associated with calcification, ECM remodeling, and tumor progression, which may contribute to treatment resistance and poor clinical outcomes." (PMID 41223185, 2025). "Matching normal lung tissue and LUAD tumor tissue IHC staining for MGP presence was unavailable." (PMID 40563443, 2025). "In addition, it appears to have a role in tumor angiogenesis; a direct relationship between the expression of MGP and tumor vascularization has been reported." (PMID 38732222, 2024). "In general, whether MGP correlates with higher or lower aggressiveness depends on the tumor type or subtype." (PMID 36977707, 2023). "Indeed, tumor formation was observed at day 20 with as few as 500 cells in MGP-expressing cells, while 2*105 cells were necessary to detect tumors with control COV318 cells at the same time point." (PMID 36977707, 2023).
tumor (continued). "Besides tumor initiation, the ectopic expression of MGP also enhanced and sustained COV318 tumor growth." (PMID 36977707, 2023). "One of the most striking and unexpected findings in our study is the strong regulatory function exerted by MGP on the transcriptional activity of OC, with over 1600 genes showing opposite regulation upon MGP ablation vs. ectopic expression in bulk tumor cells and almost 1000 in OCSC." (PMID 36977707, 2023). "Finally, MGP expression was found to correlate with poor prognosis in OC patients, and was increased in tumor tissue after chemotherapy, supporting the clinical relevance of our findings." (PMID 36977707, 2023). "TIMP3 and MGP can inhibit tumor growth, invasion, metastasis and angiogenesis." (PMID 37202394, 2023). "While the role of MGP in cancer aggressiveness remains controversial and tumor type-dependent, we argue that in those cancers where MGP appears to exert a pro-tumorigenic function, such a function could entail the activation of the CSC subpopulation." (PMID 36977707, 2023). "Since tumor initiation is a defining feature of CSC, we asked whether MGP modulates the tumor-initiating potential of OC cells." (PMID 36977707, 2023). "Along the same line, future studies should test whether MGP expression represents a proxy for the “stemness” degree of a given tumor." (PMID 36977707, 2023). "In NSCLC, it was observed that MGP gene expression could promote macrophage recruitment, neovascularization, and tumor growth." (PMID 35053080, 2022). "The difference in MGP abnormal expression of different cancers could be a result of tumor heterogeneity." (PMID 32405535, 2020). "A search and verification of downstream targets revealed that RUNX1 plays a major role in the malignant progression of Mes GBM, affecting the formation of extracellular matrix through MGP and promoting the ability of tumor cells (especially cancer stem cells) to invade into normal tissues." (PMID 31754093, 2019). "Recently, MGP expression was related to cellular differentiation and tumor progression." (PMID 30257426, 2018). "Notably, MGP was detected at variable levels in all tumor samples." (PMID 36977707, 2023). "Furthermore, MGP was found to be necessary and sufficient for tumor initiation in OC mouse models, by shortening tumor latency and increasing dramatically the frequency of tumor-initiating cells." (PMID 36977707, 2023). "Thus, MGP was required for both tumor initiation and growth." (PMID 36977707, 2023). "Thus, the expression and function of MGP in the tumor microenvironment needs further investigation." (PMID 32405535, 2020). "The literature indicates that the effect of MGP may be tumor type dependent." (PMID 25210519, 2014). "Using three spatially-enriched marker genes for each tumor subregion (CT: BCAN, CSPG5, TOP2A; Pseudo: HILPDA, IGFBP5, LGALS3; and MVP: MGP, LUM, THBS1) we identified distinct sub-populations of malignant cells from the scRNA-seq data." (PMID 41366031, 2025). "Substantiating this premise, EC4 subclass analysis identified conserved functional modules including ECM remodeling effectors (HSPG2,MGP,POSTN) and tumor niche-modifying factors (RAMP2,ACKR1,CD74)." (PMID 41394809, 2025). "Recently, we showed that MGP and RUNX2 were overexpressed in CRC tissue samples and there was a positive correlation between the two expressions in tumor mucosa." (PMID 39684309, 2024). "ELDA calculations revealed that the frequency of tumor-initiating cells increased from 1/296,618 in COV318-CTR to 1/277 in COV318-MGP cells (1071 times), in line with MGP promoting a dramatic expansion of cells with tumorigenic capacity." (PMID 36977707, 2023). "Our platform of fully patient-derived organotypic models revealed that the expression of MGP in OC cells is induced by contact with the peritoneal TME, that represents the most prominent site for metastasis and recurrence in this tumor type." (PMID 36977707, 2023).
tumor (continued). "It has been demonstrated that MGP, COL8A2, and PAPPA are effective immunological checkpoints that mediate tumor immunosuppression." (PMID 37777759, 2023). "Consistent with the previous conclusion that the EMT signature is a potential factor for tumor invasion and metastasis, the genes related to the EMT signature, including MGP, GAS1, and JUN, were found in Scissor+ cells of metastatic HGSOCs lesions." (PMID 35935940, 2022). "Matrix Gla protein (MGP) is secreted by chondrocytes and inhibits cartilage calcification, as well as reinforced angiogenesis that can favor tumor progression." (PMID 33287223, 2020). "Meanwhile, we found that MGP was also expressed in the ECM and other parts of the tumor microenvironment, such as fibroblasts and immune cells." (PMID 32405535, 2020). "Among the top differentially expressed genes between tumor and DTC samples, we found genes involved in metastasis initiation and angiogenesis, for example, MGP, BGN, POSTN and ANGPT2, to be upregulated in tumors." (PMID 28921546, 2018). "It is possible that higher tumor stage and overexpression of UBE2C and MGP in group A have contributed to the observed trend of worse outcome, because both factors have been associated with poor survival in ESCC." (PMID 27556859, 2016). "Relative expression levels of the eight genes of interest (AZGP1, BIRC5, DHCR7, IL6ST, MGP, RBBP8, STC2, and UBE2C) were compared between paired whole tissue sections and tumor-enriched specimens." (PMID 25218890, 2014). "Expression levels of GRP splice transcripts were determined in control and cancerous tissues and correlated with gene expression of MGP, GGCX, VKOR, and the tumor markers OPN and TNFα." (PMID 24949434, 2014). "Six loci (CLEC3B (previously TNA), MGP, RASSF1, SDK2, SERPINB5 and XAGE1A (previously GAGED2)) with statistically significantly higher methylation in tumor samples compared with non-tumor samples were identified." (PMID 18947422, 2008). "MGP is also enriched in ECM-related pathways, further underscoring its role in tumor progression." (PMID 40299331, 2025). "Using the HPA, AGER, MGP, PECAM1, and SLC2A1, normal lung and LUAD tumor IHC staining was accessed." (PMID 40563443, 2025). "Except for MGP, NDN,63SERP2,64FSTL1,65 and CDH566 were also closely related to tumor stemness." (PMID 38168907, 2024). "Our results strongly suggest that MGP upregulation is not a mere epiphenomenon of OC aggressiveness, but it rather reflects a functional contribution to tumor development." (PMID 36977707, 2023). "In an attempt to elucidate the biological basis of MGP enrichment in OCSC, we built on the notion that the tumor microenvironment (TME) influences several aspects of OC stemness and, therefore, could be involved in the regulation of MGP expression in OCSC." (PMID 36977707, 2023). "Thus, MGP is a novel driver in OCSC pathophysiology, with a major role in stemness and in tumor initiation." (PMID 36977707, 2023). "In addition, the effect of MGP was assessed using a subcutaneous tumor-bearing model in C57/B6 and BALB/C mice; the volume and weight of the tumor decreased significantly after MGP knockdown." (PMID 35414780, 2022). "This bioinformatic analysis process not only identifies MGP and TRPS1 as novel candidate IHC markers to support breast origin but also provides a new approach for the future selection of specific biomarkers in other tumor types." (PMID 36284362, 2022). "Our DGE analysis of non-responding gene expression areas provides some initial molecular detail and shows an upregulation of genes involved in migration, resistance, immunosuppressive function, inflammation, cancer, and tumor stroma (e.g., H2AFJ, FKBP2, MGP, A2M, and IGFBP7)." (PMID 36115838, 2022). "Contrary to periostin, MGP has not attracted much attention in the field of oral pathology and neoplasia." (PMID 34205668, 2021). "Additionally, in some advanced CC patients, MGP was also expressed in the ECM and other parts of the tumor microenvironment." (PMID 32405535, 2020).